SPP1 (secreted phosphoprotein 1)
Diseases named in the same sentence as SPP1 in open-access papers (continued):
Sharing a sentence is not in itself a finding about the gene and the disease.
cancer (continued). "The results obtained showed a negative correlation between SPP1 expression levels and various cellular processes, including metastasis, EMT, angiogenesis, DNA damage, cancer cell invasion, and cell differentiation." (PMID 38329443, 2024). "Intriguingly, antibody-mediated depletion of MARCO inhibits cancer progression and metastasis, enhancing ICB efficacy, suggesting that SPP1+ macrophages play a non-negligible role in the immunorepressive response and immunotherapeutic resistance." (PMID 34354698, 2021). "While its connections with inflammasome activity have not been previously delineated in malignant tumours, in the central nervous system, the priming step of NLRP3 activation may lead to NF-κB-mediated transcription of SPP1." (PMID 41148809, 2025). "For instance, studies have identified other macrophage subtypes, such as SPP1+ TAMs and FOLR2+ tissue-resident macrophages (TRMs), which include populations that are significant for prognosis in patients with cancer but do not conform to the classical M1/M2 polarization paradigm." (PMID 40191203, 2025). "Given that the RNAseq results could only indicate the RNA level but not the protein level of SPP1 gene expression, we retrieved the ESCA patient tissue from the cancer tissue bank in our institution and analyzed the SPP1 protein expression by western blotting." (PMID 35593388, 2022). "Therefore, the absence of CBX7 would negatively regulate the SPP1 gene expression through HMGA1b, thus reducing the E-cad, inducing the EMT, and eventually promoting the cancer progression." (PMID 33748425, 2021). "The results indicated that SPP1, TIMP1, and SERPINE1 expression appeared to be remarkably higher in CRC tissues than in the adjacent tissues, while the expression of CXCL2 was not statistically different between cancer tissues and adjacent tissues." (PMID 32936304, 2020). "Moreover, SPP1 showed a large change between the Control Current Smoker and the Cancer Nonsmoker, and RAGE showed large change between Control Never Smoker and Cancer Current Smoker." (PMID 26471143, 2015). "For examples, TNXB, SPP1 and EMCN have not previously been reported as cancer-related." (PMID 21060876, 2010).
infection (120 papers, 2008 to 2026). The state of being infected such as from the introduction of a foreign agent such as serum, vaccine, antigenic substance or organism. "Collectively, these data demonstrate that neutrophils and monocyte/macrophage cells associate with Coccidioides rapidly upon infection and suggest a novel mechanism by which monocytes differentiate into Spp1+ cells upon contact with Coccidioides." (PMID 40704794, 2025). "SPP1 or APOE knockdown in Jurkat T cells increased susceptibility to HIVGKO infection, suggesting that they have antiviral properties." (PMID 33504604, 2021). "During infection, SPP1 has to irreversibly bind to its receptor, YueB, encoded by a putative type VII secretion system gene cluster in B. subtilis." (PMID 26091431, 2015). "One of the first structural studies of phage SPP1 focused on the tail at pre- and post-infection stages, and detailed the loss of the tail tip following DNA ejection." (PMID 23170165, 2012). "The downregulation of thn-2, lys-7, and spp-1 during PA14 infection was abolished in daf-2 loss-of-function mutants." (PMID 18927620, 2008). "Our comprehensive exploration of the cystic echinococcosis ecosystem and the first discovery of SPP1+ macrophages with infection period specificity provide deeper insights into angiogenesis and the immune evasion mechanisms associated with later stages of infection." (PMID 36569953, 2022). "spp1 was the most striking example of only a few genes that, at early infection timepoints, are cell autonomously upregulated in infected cells." (PMID 40772762, 2025). "The Spp1+ macrophages represent a novel subclass that emerges only upon infection and display the highest relative abundance within infected lungs." (PMID 40704794, 2025). "Temporal comparison of the Stereo‐seq data showed that the populations of four cell types, i.e., neutrophils, Spp1+ MoMFs, plasma cells, and fibroblasts were abundantly expanded after infection." (PMID 39985260, 2025). "At the middle and late stage of infection, abundant fibroblasts and inflammatory cells were present around the parasitic microcysts, primarily composed of Spp1+ MoMFs (D79_1), forming a fibrous layer together." (PMID 39985260, 2025). "Our spatial data revealed the appearance of Spp1+ MoMFs soon after infection, indicating the continuous function of these cells through the early and late infection stages." (PMID 39985260, 2025). "Overall, the gene expression profiles observed in the monocyte/macrophage subsets indicated notable shifts in differentiation states upon infection, with the striking emergence of an Spp1+ macrophage population that displays high expression of fibrotic genes." (PMID 40704794, 2025). "The Spp1+ MoMFs were significantly enriched in the space closely adjacent to the infection foci (less than 600 μm), especially around the parasitic vesicles, as shown in a sample collected on 79 dpi." (PMID 39985260, 2025). "The cell type composition changes in the AE lesions from early to late infection stages suggested the intensified recruitment of Spp1+ MoMFs but also the disappearance of neutrophils outside the microcysts." (PMID 39985260, 2025). "We found that during M. marinum infection in adults, spp1 knockout animals displayed decreased survival over 3 weeks of infection as compared to controls." (PMID 40772762, 2025). "Our systematic investigation of SPP1 gp16.1 defective particles narrowed down the function of gp16.1 to the correct routing of DNA to the bacterial cytoplasm at the beginning of infection." (PMID 38755280, 2024). "The infection-specific abundance of Spp1 in these clusters highlight a partial EMT state in our extended analyses." (PMID 38767331, 2024). "Expression of the ligands Spp1, Cxcl2, and Cxcl3 were abundant in keratinocytes, fibroblasts, and M2-like macrophages during the infection." (PMID 38767331, 2024).
infection (continued). "Our work fills this critical gap on tailed phages particles assembly and infection mechanisms, showing that the SPP1 TCP is a tail structural component with two distinct functions." (PMID 38755280, 2024). "Compared with the control group, the expression level of SPP1 in knockdown and overexpression groups were significantly changed after the infection of lentivirus." (PMID 38956502, 2024). "We will also explore the specific functions and in-depth mechanisms of SPP1+ macrophages further to fully elucidate the important role of this cell population during infection." (PMID 36569953, 2022). "We characterized the dynamics of immune and endothelial cells during each infection phase and identified a macrophage population that emerged specifically during the later phase of infection, which were termed SPP1+ macrophages." (PMID 36569953, 2022). "An SPP1+ macrophage subset with immunosuppressive and pro-angiogenic functions was identified in the late infection stage." (PMID 36569953, 2022). "Our scRNA-Seq results delineated the immune cell and endothelial cell landscape during different E. granulosus infection periods and revealed that SPP1+ macrophages are important in immunosuppression and angiogenesis during the later stages of infection." (PMID 36569953, 2022). "The m5 mutant also exhibited enhanced resistance to infection by SPP1, a lytic phage from a different bacteriophage family (Siphoviridae)." (PMID 34399609, 2021). "Consistent with the results from RNA sequencing, infection induced expression of antimicrobial proteins (nlp-30, nlp-34 and spp-1) and lysozyme (ilys-2) was severely compromised by rnp-6 G281D substitution." (PMID 32538777, 2020). "Here, employing a genetic orthogonal control of ζ and ε levels, the fate of bacteriophage SPP1 infection was analyzed." (PMID 33333975, 2020). "In an SPP1 infection study, we observe that ΔpgcA and ΔgtaB are resistant to the infection, consistent with previous observations." (PMID 31589605, 2019). "The interaction of the SPP1 tail fiber with YueB triggers ejection of SPP1 DNA through its tail tube, committing the phage to infection." (PMID 30544981, 2018). "Transcriptomics, proteomics, and metabolomics combined with systematic knock-outs and sensitive phenotyping assays in different infection settings appears as a promising approach to deliver a complete functional map of SPP1." (PMID 30544981, 2018). "The intensive research that followed on the molecular mechanisms supporting SPP1 infection rendered it one of the best characterized phages of Gram-positive bacteria." (PMID 30544981, 2018). "SPP1 infection is initiated by reversible adsorption of the viral particle to glycosylated teichoic acids followed by irreversible binding of SPP1 to YueB." (PMID 30544981, 2018). "We also observed the appearance of a similar 44-kb plasmid band after infection with the wt SPP1 phage of cells bearing the natural pUB110 plasmid." (PMID 29018417, 2017). "After infection with the wt phage the appearance of plasmid DNA that migrates with the bulk of SPP1 DNA (i.e., a multimeric plasmid DNA band of 44-kb) was observed." (PMID 29018417, 2017). "Infection of lentivirus containing WT iOPN plasmid increased OPN expression in WT macrophages and restored iOPN expression in OPN-deficient (Spp1−/−) macrophages." (PMID 27026194, 2016). "SPP1 gp7, present at an estimated three copies per virion, is proposed to bind DNA in a non-specific manner to control genome ejection at the onset of infection." (PMID 26147978, 2015). "PFGE experiments were used to analyze the rate of synthesis and the structure of viral DNA that accumulated in wt SPP1 and in SPPlΔA infections." (PMID 23119018, 2012). "Previously, it was shown that SPP1 theta-type replication initiates at min 3 after infection, RDR initiates at min 7, and processive packaging of a concatemer formed by ∼4–5 genome equivalents into empty viral procapsids initiates at min 12 post-infection." (PMID 23119018, 2012).
infection (continued). "Immediately after infection, SPP1 transcribes a number of genes involved in recombination and replication from PE2 and PE3 promoters." (PMID 23119018, 2012). "Compared to AdV-GFP controls, AdV-Cre and AdV-shSpp1 infection led to successful targeted knockdown of Sox9 and Spp1 respectively." (PMID 22046352, 2011). "The expression of SPP1 is enhanced in T cells during bacterial infection in order to recruit macrophages to the infection site and to improve cell-mediated immunity (Th1) by increasing the secretion of Th1 cytokines." (PMID 19765294, 2009). "Because knockdown of basal expression of thn-2, lys-7, and spp-1 by RNAi resulted in enhanced susceptibility to PA14, suppression of their expression during infection should compromise host defense." (PMID 18927620, 2008). "Using quantitative RT-PCR, we confirmed that known host defense effectors, including thn-2, lys-7, and spp-1 are downregulated during PA14 infection." (PMID 18927620, 2008). "Overall, these results implicate DAF-2 and DAF-16 in the downregulation of thn-2, lys-7, and spp-1 during PA14 infection." (PMID 18927620, 2008). "First, the intestine is the site of PA14 infection, and the major site of expression of host defense genes including spp-1 and lys-7." (PMID 18927620, 2008). "Interestingly, moderate expression of Spp1 was also observed at the termination of lineage two, suggesting that alveolar macrophages begin to express Spp1 after infection." (PMID 40704794, 2025). "However, during the course of infection, these usually well-correlated Th1 cytokines show alternating patterns in IE upregulation of SPP1 contrasted by the L upregulation of IFNG." (PMID 39863683, 2025). "VSV‐M51 infection resulted in SPP1/HMOX1 downregulation in T98 cells." (PMID 40495644, 2025). "At 24 h post-infection, robust immune infiltration is detected in the lung, marked by high levels of inflammatory PD-L1+ neutrophils and fungal-contact-dependent pro-fibrotic Spp1+ macrophages." (PMID 40704794, 2025). "The rapid induction of Spp1+ macrophages suggests that anti-fibrotic strategies might be considered early in infection to prevent inappropriate induction of tissue remodeling." (PMID 40704794, 2025). "Together, these findings suggest that upregulation of Spp1 may initially represent an attempt to control disease following direct contact with Coccidioides but may ultimately be detrimental to infection outcomes." (PMID 40704794, 2025). "SPP1 gp16.1 could exert its function in infection either by controlling DNA ejection from the viral particle or by being ejected into the bacterium to promote host takeover." (PMID 38755280, 2024). "The SPP1 signaling pathway was activated and increased between the macrophages, B cells, hepatocytes, hepatic stellate cells, macrophages, and T-cells in clusters 1 and 2 at 6 w after infection." (PMID 39590301, 2024). "HLA and SPP1 expression suggests M2 polarization and antigen presentation may be shifting despite a lock of a change in overall M2 polarization during dormant infection." (PMID 39563367, 2024). "While we excluded patients under conditions that could influence Spp1 levels, such as those undergoing immunotherapy or experiencing infection, the complex comorbidities of our patients might have introduced confounding variables into the results." (PMID 38775192, 2024). "In addition, the insulin-like growth factor-1 (IGF-1), visfatin, and secretory phosphoprotein 1 (SPP1) signaling pathways were increased after infection with schistosomes." (PMID 39590301, 2024). "Interestingly, STY ΔchiA infection completely rescued spp1 expression and significantly upregulated abf2 expression, indicating an important function of chitinase in restricting the antimicrobial responses of the host." (PMID 35482710, 2022).
infection (continued). "Our study provides the first comprehensive resolution of an immune landscape in mouse liver during different E. granulosus infection periods and highlights the important role of SPP1+ macrophages in the later stages of infection, which provides targets for immunotherapy." (PMID 36569953, 2022). "Spp1–integrins/Cd44 were present only in the 6-month samples, and Cxcl4–Cxcr3 and Entpd–Adora2a were present only in the 3-month samples, while Cxcl16–Cxcr6 expression gradually decreased between T cells and endothelial cells as infection progressed." (PMID 36569953, 2022). "APOE and SPP1 restrict HIVGKO infection in both Jurkat T cells and primary CD4+ T cells." (PMID 33504604, 2021). "In the later stage of infection, focal adhesion pathway was associated with ECM receptor interaction pathway through SPP1, col6a2, COL3A1 and VTN proteins, while focal adhesion pathway linked with leukocyte transendothelial migration pathway by RAC1 and LOC733637." (PMID 32632500, 2020). "Spp1−/− mice all died, while 50% of WT mice were alive 5 days after infection." (PMID 27026194, 2016). "Interestingly, SPP-5 is markedly more closely related to SPP-2 (79% similar) and the other infection-induced SPPs than are either SPP-1 or SPP-12." (PMID 27153332, 2016). "Several Caudovirales phages, such as P22, φ29 and HK97, have served as models for understanding the structure and assembly of phage capsids, while particular Siphoviridae, including phages λ, T5, SPP1 and p2, have been instrumental in assessing the assembly and role of the tail during infection." (PMID 26147978, 2015). "The present findings showed that after PA14 infection, the mRNA levels of selected immune-related genes (namely, irg-1, hsf-1, lys-1, spp-1, and abf-1) (Ctrl + PA14) were significantly suppressed 20% to 80% compared with that of the uninfected group (Ctrl + OP50) without Se(IV) treatment." (PMID 25147937, 2014). "YueB is the membrane receptor essential for phage SPP1 infection." (PMID 23861817, 2013). "A polymorphism in this region could potentially affect the binding of these two TFs and influence the rapidity of the response of SPP1 to infection." (PMID 19765294, 2009). "Intestine-specific expression of fat-3 restored the expression of seven of the eight the down-regulated infection-response genes, including the immune-specific genes spp-1, lys-7 and F08G5.6, indicating that fat-3 is required in the intestine to regulate basal gene expression." (PMID 19023415, 2008). "To examine whether spp1 might be acting through alterations in granuloma organization or stability, we harvested infected spp1 knockout and control adult zebrafish at 2 weeks post-infection, a timepoint when organized mature granulomas emerge consistently in wild-type animals." (PMID 40772762, 2025). "Infection with adenovirus encoding shRNA against c-Jun (shc-Jun), but not against p65 (shp65), abolished PARP1 overexpression-induced upregulation of CyclinD1, Pcna, Mmp9, Pxn, Spp1 and Tnc genes, suggesting that c-Jun mediated the effects of PARP1 on VSMC proliferation and migration." (PMID 40744995, 2025). "Moreover, Spp1+ MoMFs may facilitate angiogenesis in the infection foci, which can provide nutrients for the pathogen, thus accelerating metastasis and exacerbating disease severity." (PMID 39985260, 2025). "However, gWTA also plays an important role for SPP1 infection as well." (PMID 34399609, 2021). "This suggests that the initial, reversible stage of infection involves a CBM-mediated attachment to saccharidic moieties on the host cell surface, similar to what has been shown for SPP1." (PMID 41012688, 2025). "A study in OPN/SPP1 knockout mice showed that there was disorganized wound remodeling and defective macrophage infiltration after injury or infection." (PMID 38919629, 2024). "The qRT-PCR results revealed that the SPP1 expression and CD44 increased in the liver at 6 w after infection." (PMID 39590301, 2024).